BRAF (B-Raf proto-oncogene, serine/threonine kinase)
Diseases named in the same sentence as BRAF in open-access papers (continued):
Sharing a sentence is not in itself a finding about the gene and the disease.
melanoma (continued). "This speculation was supported by another study showing that initially well responded BRAF-mutant melanoma cells to PLX4720 became tolerant after certain period of treatment by reactivating ERK/MAPK in the areas of high stromal density." (PMID 30680600, 2019). "In summary, endogenous expression of RAC1P29S in BRAF-driven melanoma produces a less melanocytic and more mesenchymal differentiation state and generates resistance to the BRAF inhibitor PLX4720, which can be substantially reversed by co-treatment with an SRF/MRTF inhibitor." (PMID 31257073, 2019). "The BRAF-ERK kinase pathway activates ETS family proteins in melanoma, thyroid cancer and glioma." (PMID 30709063, 2019). "It is noteworthy that although TNFα promoted BRAF ubiquitination in BRAFV600E-expressing 1205Lu melanoma cells, the treatment only moderately affected MEK/ERK activities, which is consistent with the results that p-MEK/p-ERK levels were insensitive to ITCH knockdown." (PMID 31015455, 2019). "Indeed a decrease in the level of Ubiquitin Ligase RNF125 has been described to correlate with SOX10/MITF expression and to promote BRAF inhibitors resistance in melanoma." (PMID 31118886, 2019). "Moreover, BRAF-mutant melanomas are considered more aggressive than wild-type tumors, but the role of this genetic alteration as predictive biomarker for immunotherapy is debated." (PMID 31179334, 2019). "Based on our findings that all thyroid cancer cases (6.5%) occurred after the first melanoma diagnosis and due their common papillary pathological type (PTC), although our small patient cohort, we aimed to assess the rate of BRAF V600E mutation in this patient cohort." (PMID 31164959, 2019). "Therapeutic interventions in melanoma cases are evolving rapidly, and the role of metastasectomies in the era of immunotherapy and BRAF and MEK-targeted therapies is largely unknown." (PMID 30899610, 2019). "In addition, we showed an association between ZEB1-AS1 expression levels with BRAF/RAS status and with an invasive phenotype in melanoma and suggested this lncRNA directly or indirectly regulates potential genes and pathways." (PMID 31383874, 2019). "We assessed whether inhibiting this pathway by adding kinase inhibitors trametinib or pazopanib to paclitaxel chemotherapy improved outcomes in patients with advanced BRAF-wt melanoma in a phase II, randomised and open-label trial." (PMID 30428063, 2019). "In BRAF-(V600E)-mutated melanoma, pharmacological Cu sequestration with a clinically used copper chelator, ammonium tetrathiomolybdate (TTM) inhibits MEK1/2 kinase activity and reduces mutant BRAF-driven growth in melanoma cell lines resistant to BRAF or MEK1/2 inhibitor." (PMID 30792807, 2019). "The relevant data on ADRs for the dabrafenib/trametinib combination were available only from the COMBI-d trial, a randomized double-blind phase III trial evaluating dabrafenib/trametinib versus placebo/trametinib in previously untreated patients with BRAF-mutant melanoma." (PMID 31653096, 2019). "Sunitinib, a broad-spectrum tyrosine kinase inhibitor that primarily targets VEGF pathways but has some collateral inhibition of these pathways, can be used for BRAF-wild-type or drug-resistant BRAF-mutant melanomas, but response rates are low and toxicity is significant." (PMID 31615091, 2019). "Notably, ubiquitination of endogenous BRAF was induced by TNFα or IL-1β treatment in both melanocytes and melanoma cells, while depletion of ITCH abrogated TNFα-stimulated BRAF ubiquitination." (PMID 31015455, 2019).
melanoma (continued). "In melanoma, colorectal, and lung cancer, BRAF p.V600E is a well-known druggable (anti-EGFR therapy) hotspot affecting the kinase domain of the protein, recently classified as a class I mutant, with the strongest kinase activity, constitutive MAPK cascade, and RAS-independent." (PMID 31197119, 2019). "Despite the significant advancements in immunotherapy and BRAF inhibitor therapies, melanomas still represent a challenge in oncology since these treatment modalities will certainly extend life expectancy, but not provide a cure or at least a transformation to a chronic disease stage." (PMID 31468706, 2019). "In melanoma, PD-L1 is highly expressed in cell lines resistant to BRAF inhibitors (BRAFi)." (PMID 31340499, 2019). "An open-label phase II trial treated 24 patients with nonresectable, previously treated BRAF-mutated melanoma BM using vemurafenib." (PMID 31803366, 2019). "We thus present a suitable candidate for the development of novel treatment options based on G4 targeting, which may be particularly relevant in the context of resistance to targeted therapies of BRAF-mutant melanoma cells." (PMID 31635389, 2019). "Thus, the fact that the MAPK pathway regulates MITF expression and function is critical, considering that melanoma patients are treated with BRAF and MEK inhibitors (MAPKi)." (PMID 30277012, 2019). "Furthermore, it has been demonstrated that increased MITF expression renders melanoma cells resistant to BRAF pathway inhibition." (PMID 31416288, 2019). "Genomic biomarkers paired with targeted therapies have proved highly efficacious in some cases, such as HER2 amplification and trastuzumab in breast cancer, BRAF mutation and combined BRAF and MEK inhibition in melanoma and EML4-ALK fusions and crizotinib in lung adenocarcinoma." (PMID 31060263, 2019). "Cobimetinib (GDC-0973, XL518) was approved for melanoma in tandem with BRAF inhibitor vemurafenib." (PMID 31652660, 2019). "The next step could include the evaluation of these circulating lncRNAs as predictive factors in a randomized study including melanoma patients receiving BRAF+MEK inhibitors and immunotherapy." (PMID 31231466, 2019). "Consistent with this hypothesis, we found that MCL-1 dependence was minimally changed after BRAF inhibition in melanoma cells derived from a patient who was resistant to BRAF/MEK inhibitors." (PMID 31727958, 2019). "Importantly, inhibition of YAP/TAZ function in melanoma cells was shown to overcome resistance to BRAF inhibitors." (PMID 31058846, 2019). "Therefore, increased matrix stiffness is sufficient to protect BRAF-mutant melanoma cells from BRAF inhibition, while YAP/TAZ activation induces resistance to therapy targeting the RAS/RAF pathway." (PMID 31109009, 2019). "Therefore, the reported results show that the downstream functions of BRAF, such as melanoma growth, mobility and invasiveness are irreparably compromised, suggest that (Bu2Sn)2TPPS and (Bu3Sn)4TPPS act downstream of BRAF mainly bypassing its functions." (PMID 31801187, 2019). "The induction of autophagy in melanomas by hyperactivation of oncogenic BRAF is documented." (PMID 31841566, 2019). "No study, however, has been carried out to determine the BRAF V600E mutation status and p16 expression in melanoma within the Nigerian population." (PMID 31139472, 2019). "The BRAF/MEK/ERK pathway is crucial to melanoma cell growth." (PMID 31015455, 2019). "The A375 human melanoma cell line expresses mutant V600E BRAF and is sensitive to ERK inhibition." (PMID 31745079, 2019). "Importantly, the RAC1 P29S mutation was more frequent in melanomas that were wild type for both NRAS and BRAF." (PMID 31027363, 2019). "Benign growths such as melanocytic nevi have been found to contain hyperactive BRAF mutations similar to melanomas but do not undergo tumorigenesis due to the maintenance of the senescent state." (PMID 30850015, 2019).
melanoma (continued). "Taken together, for 27 drugs in our melanoma cell line panel, genomic biomarkers could only be found for BRAF inhibitors, whose drug sensitivity were predicted from oncogenic BRAF itself." (PMID 31253656, 2019). "The top drug combination predicted for melanoma with BRAF gene mutations included a known melanoma drug, vemurafenib, in combination with another agent not currently used for melanoma, tretinoin." (PMID 30820351, 2019). "Proteomics analyses showed differences in expression of proteins related with fatty acid metabolism, melanogenesis and extracellular space between BRAF mutated and BRAF non-mutated melanoma tumors." (PMID 31076580, 2019). "Moreover, knockdown of c-Jun is necessary and sufficient to suppress the expression of PD-L1 in melanoma cells that are either sensitive or resistant to BRAF inhibition." (PMID 31341011, 2019). "Therefore, recent pre-clinical study-based clinical trials have attempted to identify optimal drugs (e.g., immune checkpoint inhibitors or histone deacetylase (HDAC) inhibitors) that improve the anti-melanoma effects of BRAF and MEK inhibitors." (PMID 31514399, 2019). "This subgroup of patients could thus prove to be a limitation for BRAF IHC usage in prognosticating melanomas." (PMID 31039200, 2019). "In addition, PLX-4720 BRAF inhibitor–resistant melanoma cells have shown resistance to BRAF inhibitor by activating of PI3K/AKT signaling and escaping from MAPK pathway." (PMID 30940145, 2019). "No targeted therapies are currently available for melanoma that does not contain BRAF mutations or melanomas that have become resistant to BRAF inhibitors." (PMID 30824801, 2019). "SAMMSON is expressed in 90% of human melanomas and is essential to the viability of melanomas, irrespective of BRAF or NRAS mutational status." (PMID 31416288, 2019). "This predictions were verified in in vitro experiments with A375 melanoma cells subjected to treatment with the two BRAF inhibitors sorafenib and B0R (2,6-difluoro-N-(3-methoxy-2H-pyrazolo[3,4-b]pyridin-5-yl)-3-[(propylsulfonyl) amino]benzamide) at different doses, alone or in combination." (PMID 30987166, 2019). "Taken together, we have identified and characterized synergistic kinase inhibitor treatments targeting the MAPK pathway and the cell cycle that could be promising alternatives for drug-resistant melanoma patients or wild-type BRAF patients." (PMID 30728057, 2019). "As a matter of fact, only a few types of cancer have been successfully treated with a single drug, e.g., imatinib in chronic myeloid leukemia, gefitinib (EGFR inhibitor) in mutant EGFR non-small cell lung cancer, and PLX4032 (BRAF inhibitor) in mutant BRAF melanoma." (PMID 30909600, 2019). "Therefore, we selected this drug combination for prospective validation in the A375 BRAF-mutant melanoma cell line." (PMID 30820351, 2019). "In a Chinese population examined by Sanger sequencing of exon 15, kinase impaired BRAF mutations involving codons 594 and 596 were observed in 7 (3.4%) of 208 mucosal melanomas and 6 (1.1%) of 544 non-mucosal melanomas." (PMID 31277584, 2019). "Strikingly, the BRAF and NRAS mutation profiles in mucosal melanoma are closer to those found in cancers such as lung cancer, suggesting that mutations in mucosal melanoma could be linked to some genotoxic agents that remain to be identified." (PMID 31398831, 2019). "Inhibition of BRAF is also a promising approach in treating malignant melanoma." (PMID 31370278, 2019). "Nonetheless, a single-gene aberration is not always predictive of treatment response as has been observed for the oncogenic BRAF mutations, which predict BRAF inhibitor response in melanoma, but not necessarily in non-melanoma cancers." (PMID 29272324, 2019).
melanoma (continued). "Now, the initiation and development of melanoma were identified to be caused by dysfunctions of oncogenic and tumor suppressor pathway, and different biomarkers have been identified to be highly significant and relevant in the context of melanoma, including BRAF, NRAS, and C-KIT." (PMID 30832692, 2019). "By performing ChIP we could show that PAX3 bound the region covering the P2 site, further supporting that this site, which is also important for the regulation by BRAF is used by PAX3 in melanoma cells." (PMID 30277012, 2019). "In this study BRAF, NRAS, KRAS, HRAS, PIK3CA and KIT mutations were examined in melanomas." (PMID 31277584, 2019). "Thus, simultaneous pharmacological inhibition of DHODH and BRAF has been reported to decrease the progression of melanoma in cell lines and in mouse xenograft models." (PMID 31108873, 2019). "PGC1A and MITF are a notorious pair implicated in overcoming melanoma’s glycolytic dependence and in development of rapid resistance to BRAF-inhibitor therapy, a cornerstone in recent melanoma therapeutics, and are currently in clinical trials as an adjuvant in melanoma immunotherapy." (PMID 31547367, 2019). "Indeed, while several conjunctival melanocytic nevi harbor BRAF mutations, TERT promoter mutations are detectable only in melanomas and premalignant lesions (such as PAM with atypia), playing a role in tumor progression." (PMID 31683701, 2019). "c Expression levels of complex I subunit NDUFB8 in BRAF mutated melanoma (BRAFV600E; n = 24) and BRAF wild type melanoma (no BRAFV600E; n = 23)." (PMID 30971321, 2019). "Thus, S142 phosphorylation by ERK plays a dominant role over S211 phosphorylation in TFEB regulation in BRAF-mutant melanoma." (PMID 30979895, 2019). "In BRAF-mutant melanoma, a second MEK inhibitor MEK162 showed similar responses." (PMID 31426419, 2019). "Our results demonstrate that BRAF immunohistochemistry could be an integral part in assisting selection of patients with intermediate thickness melanomas for sentinel node dissection." (PMID 31039200, 2019). "In addition to TAMs, the assessment of CD8+ effector T cells is important to augment the anti-tumor response in BRAF inhibitor-resistant melanomas." (PMID 31514399, 2019). "In melanoma, several studies have also shown the efficacy of utilising ctDNA for monitoring patients with BRAF mutant tumours, particularly in the context of treatment response and identification of mechanisms of resistance to BRAF inhibitors." (PMID 31727009, 2019). "A recent phase I dose escalation clinical trial in melanoma has shown that another HSP90 inhibitor (XL888) in combination with a specific anti BRAF inhibitor (vemurafenib) has clinical activity in patients with advanced BRAFV600-mutant melanoma, with a tolerable side effect profile." (PMID 31861612, 2019). "In order to find new combinations of kinase inhibitors to treat BRAFi-resistant melanoma, delay or avoid development of resistance, we have screened a 274-kinase inhibitor library in BRAF mutant melanoma cell lines, sensitive and resistant to different BRAF inhibitors." (PMID 30728057, 2019). "Acquired resistance during BRAF inhibitor therapy remains a major challenge for melanoma treatment." (PMID 31514305, 2019). "Similarly, the reactivation of the PI3K/Akt-CREB-AEBP1-NF-κB pathway showed to contribute to BRAF inhibitor-resistant phenotype in melanoma treatment." (PMID 30717768, 2019). "Thus, the “BRAF-TFEB-autophagy-lysosome” axis represents an intrinsic regulatory pathway in BRAF-mutant melanoma, coupling BRAF signaling with TGF-β signaling to drive tumor progression and chemoresistance." (PMID 30979895, 2019). "They reported localization of the protein kinase inhibitor vemurafenib within tumor regions of human malignant melanoma, where it specifically bound to its targets, BRAF mutated proteins, as opposed to BRAF negative tumor regions." (PMID 31628408, 2019).
melanoma (continued). "We also show that the atypical BRAF and NRAS mutations found in mucosal melanomas have particular effects on protein activities, which could be essential for the transformation of mucosal melanocytes." (PMID 31398831, 2019). "In summary, the findings of the present study refine our understanding of the role of BRAF and NRAS mutations in mucosal melanomas and could pave the way for therapeutic intervention." (PMID 31398831, 2019). "This study reviews the management of BRAF-V600E mutant melanoma with ependymal involvement." (PMID 30972290, 2019). "Augmented mitochondrial respiration is a key resistance mechanism in BRAF-mutant melanomas but, as we show in this study, this dependence on mitochondrial respiration may also be exploited therapeutically." (PMID 30971321, 2019). "However, dabrafenib has also had a number of serious side-effects reported, some of which can be life threatening, including, but not limited to, primary cutaneous malignancies, tumor promotion in BRAF wild-type melanomas, and serious febrile drug reactions." (PMID 30975211, 2019). "In addition, high levels of serum lactate were observed in patients with BRAF mutant melanomas, providing evidence of linking oncogenic BRAF/ERK signaling to aerobic glycolysis in a clinical setting." (PMID 30487597, 2019). "Although they constitute <2% of all incident cancers, melanoma is the fifth most lethal due to an intrinsic resistance to standard chemotherapy, radiation therapy, targeted therapies such as BRAF inhibitors, and immunotherapy such as immune checkpoint inhibitors (ICI)." (PMID 31547367, 2019). "Furthermore, because of the known heterogeneity of tumors even within a given cancer type or genetically defined subtype (such as BRAF V600E melanoma) there is a need to perform these combination screens across large numbers of models." (PMID 30777010, 2019). "In review of the published literature using the terms conjunctiva, melanoma, BRAF, KIT, pembrolizumab, ipilimumab, interferon and genetics, we found a 2016 study on the efficacy of anti-PD-1 agents in acral and mucosal melanomas supported its use in clinical practice." (PMID 30909967, 2019). "Hence, the mitogen-activated protein kinase (MAPK) pathway is the most relevant oncogenic signaling altered in melanoma, an evidence that guided the development of targeted therapies using BRAF and MEK inhibitors." (PMID 31672982, 2019). "In this study, we compared two human melanoma cell lines that differed in their oncogene profile (BRAFV600E and BRAFwt) causing altered sensitivities to classical chemotherapeutics and PLX4032, an inhibitor of mutated BRAF." (PMID 30631106, 2019). "NGS examination using AmpliSeq sequencing panel among 699 advanced melanomas revealed 6% non-codon 600 BRAF mutations." (PMID 31277584, 2019). "In this context, BRAF-inhibitors could represent a useful therapeutic strategy for treatment-refractory patients with either melanoma or thyroid cancer." (PMID 31762942, 2019). "We thus present a starting point for the future development of therapeutic interventions based on G4 targeting that may be of particular relevance in the context of resistance to targeted therapies of BRAF-mutant melanoma cells." (PMID 31635389, 2019). "In this case, specifically in the BRAFV600E-mutant background, melanoma patients treated with a combination of a BRAF inhibitor with a MEK inhibitor exhibited improved progression-free survival when compared to patients treated with BRAF inhibitor alone." (PMID 31640753, 2019). "Activation of the EGFR pathway was also identified in BRAF-inhibitor-resistant melanoma." (PMID 31514305, 2019). "Despite this, ipilimumab has since been approved for BRAF V600 wild-type melanomas, melanomas after surgery (NCT00636168), unresectable or metastatic melanomas (CHECKMATE-067/ NCT01696045), intermediate or poor-risk advanced RCCs (CHECKMATE-214), and metastatic CRC (CHECKMATE-142)." (PMID 30975211, 2019).